CD4 (CD4 molecule)
Diseases named in the same sentence as CD4 in open-access papers (continued):
Sharing a sentence is not in itself a finding about the gene and the disease.
periodontitis (continued). "Furthermore, naive B cells were barely visible in healthy periodontal tissues, and most of the T cells that infiltrated the healthy gums were resting memory T cells, while periodontitis tissues generally contained a higher proportion of activated CD4 memory T cells." (PMID 33109155, 2020). "Also, at cervical lymph nodes, CD4+Foxp3+ cells were more frequent within the CD4+ compartment at day ten post-periodontitis induction (5% increase), although, at the same time point, the percentage of Foxp3+ cells within the CD4+CD25+ population was significantly reduced (50% less)." (PMID 33149125, 2020). "Moreover, the percentage of CD4+ T cells producing IL-17 significantly increased in periodontitis." (PMID 31416146, 2019). "Chronic periodontitis in HIV-seropositive subjects is similar in terms of mean PPD, GR, PI, and BI to that in presumably healthy aged-matched control subjects, and a low CD4+ T-cell count does not appear to be a risk factor for increased frequency or severity of chronic periodontitis." (PMID 22970354, 2012). "Other viruses found in children affected by Hydroa Vacciniforme and periodontitis were HHV-6 and HHV-7, which infected CD4+ T lymphocytes, macrophages, monocytes, and fibroblasts." (PMID 40871317, 2025). "These subclusters include CD4+, MAIT, CD8+, γδ T-cells, Treg, TH17, and NK T-cells, which are consistently observed across different studies, albeit with varying proportions in periodontitis." (PMID 38919613, 2024). "Like pro-inflammatory CD4+ T-cells, the pro-inflammatory CD8+ cytotoxic T lymphocytes likely promote periodontitis whereas the pro-resolving CD8+ Tregs help prevent or reduce it." (PMID 38919613, 2024). "In a canine study, although the frequency of CD4 + and CD8 + T cells in the circulating blood of dogs with periodontitis was higher than that in healthy controls, the difference was not significant." (PMID 39342169, 2024). "In another parallel experiment, our research group established a beagle periodontitis model and confirmed that PGRN can also modulate CD4 + T differentiation into Treg, while in-vitro evidence needs to be provided in the future." (PMID 38689292, 2024). "Consistent with previous findings, we found that a higher level of STAT3 signaling in BM-MSCs from periodontitis mice can induce more IL-17 production and higher expression levels of RORC in CD4 T cells." (PMID 37490712, 2023). "Discovering the crucial pathways to control the differentiation of CD4+ T cells may bring a new direction for the treatment of periodontal diseases through regulating immunity and achieving a balance between fighting infection and reducing the tissue destruction in periodontitis." (PMID 35222410, 2022). "Another weak relationship in whole blood samples was found between skull types and CD14+ (p = 0.034), CD3+ CD4+ CD8+ (p = 0.034), as well as periodontitis stages three and four and CD3+ CD4+ CD8+ (p = 0.044)." (PMID 36261500, 2022). "Compared to SH, CD4 + T cells were significantly activated by periodontitis microbiota, with the accumulation of IFNγ+ CD4 (p < 0.05), IL17+ CD4 (p < 0.05), and IL22+ CD4 (p < 0.05) T cells in the small intestine." (PMID 35756043, 2022). "On the contrary, the frequency of Foxp3+ cells within the CD4+CD25+ compartment, which only includes activated T cells, was reduced during periodontitis, suggesting an imbalance between effector and regulatory T responses." (PMID 34012448, 2021). "The opposite was observed when we analyzed the frequency of CD4+ cells among CD45+ cells, indicating CD4+ T cell proliferation during periodontitis." (PMID 34012448, 2021). "The populations of TNF-α- or IL-17A-producing memory CD4+ and CD8+ T cells were significantly higher in the regional lymph nodes of HFD-fed mice with periodontitis than in those of mice fed a NCD." (PMID 35069547, 2021).
periodontitis (continued). "We found significantly more TNF-α- or IL-17A-producing CD4+ and CD8+ T cells in the regional lymph nodes of mice with ligature-induced periodontitis than in control lymph nodes." (PMID 35069547, 2021). "Analyzing a subset of CD4+ and CD8+ T lymphocytes, we observed that the population of memory T cells (CD44+CD62L–) increased in the regional lymph nodes of HFD-fed mice with periodontitis, whereas the population of naïve T cells (CD44–CD62L+) decreased." (PMID 35069547, 2021). "As expected, there was an imbalance between the proliferation of effector T cells (CD4+CD25+Foxp3-) and Tregs (CD4+CD25+Foxp3+) during the experimental periodontitis." (PMID 34012448, 2021). "Of the population of CD4+ and CD8+ T cells that had infiltrated the inflamed gingiva, the percentage of CD44+ memory T cells was lower in periodontitis-induced obese mice treated with miR-25-3p inhibitor." (PMID 35069547, 2021). "This led to the significant negative association of plasma cells with memory B cells, resting dendritic cells, resting CD4 memory T cells, activated dendritic cells, M1 macrophage, M2 macrophage, or TFH between healthy controls and periodontitis tissues." (PMID 33109155, 2020). "The flow cytometry analysis of CD4+CD25+Foxp3+ cells in cervical lymph nodes and spleens of animals affected with experimental periodontitis revealed significant changes in the Foxp3 expression, Treg frequency, and Treg number." (PMID 33149125, 2020). "In comparison to the CCUS lesions, CD3, CD4, CD8, mast cells, CD204 and FoxP3+ cell numbers in periodontitis lesions were significantly less, while the numbers of infiltrating CD20 and Mum1+ plasma cells were indistinguishable between these two lesions." (PMID 31923271, 2020). "It has been also reported that expression of PD-1 and PD-L1 in peripheral CD4+ T lymphocytes and CD8+ T lymphocyte of chronic periodontitis patients was upregulated." (PMID 30923536, 2019). "The general concept of Th1- and Th2-type CD4 + T cells established in other chronic inflammatory diseases is not suitable for periodontitis due to the contradictory results of previous studies." (PMID 39342169, 2024). "However, in peri-implantitis, CD4-positive cells were more prevalent than CD8-positive cells (CD4/CD8 ratio of 1.2), indicating more severe immune dysregulation and immune destruction compared to periodontitis." (PMID 39555067, 2024). "Eleven critical immune cell types in periodontitis were screened by LASSO regression: naive B cells, memory B cells, plasma cells, naive CD4 T cells, activated memory CD4 T cells, gamma delta T cells, resting NK cells, M0 macrophages, resting dendritic cells, resting mast cells, and neutrophils." (PMID 38308306, 2024). "In our study, we found a significant decrease in the CD4 + /CD8 + ratio in gingival tissue with periodontitis (ACS + P group and no ACS + P group) compared to the no ACS + G group, quite similar to a previous research." (PMID 38451305, 2024). "In addition, during periodontitis, increased expression levels of the FOS and JUN genes were observed in CD4+ T-cells, indicating their importance in cell activation." (PMID 37834287, 2023). "For example, myeloid cells in gingival tissue of patients with T2D periodontitis could produce higher levels of IFN-γ and IL-10, while CD4+T could produce higher levels of IL-8." (PMID 36131931, 2022). "In our study, patients with DP or DNP showed correlations between butyrate metabolism-related metabolites and periodontal clinical index (BI, PD, AL), Th17%, Treg/Th17 ratio, CD4+ PDL1%, and CD8+ PD1%, indicative of the relationship between the severity and immunological state of periodontitis." (PMID 36519166, 2022). "A higher proportion of PBMC cells related to wound healing (CD3+, CD3+ CD4+ CD8−, CD14+) were found in the PRF of control, periodontitis and neoplasia groups compared to the respective blood samples, which implies a positive outcome associated with clinical PRF usage in canine patients." (PMID 36261500, 2022).
periodontitis (continued). "In this experimental model, a purified population of senescent or non-senescent CD4+ T lymphocytes can be transferred and periodontitis can be induced in these mice." (PMID 35269683, 2022). "The results showed that central memory CD4 T cell, MDSC, Effector memory CD8 T cell, plasmacytoid dendritic cell, activated CD8 T cell, activated dendritic cell and monocyte were highly expressed in periodontitis and PD." (PMID 36545026, 2022). "Collectively, these studies suggest that the number of CD4+CD25+Treg may change during the pathological process of gingivitis and periodontitis." (PMID 34234776, 2021). "Due to the significant increase in the total cell number of cervical lymph nodes, when we measured the frequency of CD4+ cells among all cell types (including non-leukocytes), the percentage decreased in animals with periodontitis compared to healthy mice." (PMID 34012448, 2021). "However, the other subtypes of T cells, including resting CD4 memory T cells, CD8 T cells, follicular helper T cells and regulatory T cells (Tregs), were relatively lower in periodontitis tissues, when compared to those in healthy tissues." (PMID 33109155, 2020). "We detected a sharp reduction in the Foxp3 MFI on CD4+CD25+Foxp3+ cells after 5- and 10-days post-periodontitis induction at all cervical lymph-nodes (≈ 28% reduction) and spleens (≈ 17% reduction), although the effect was more significant in cervical lymph nodes." (PMID 33149125, 2020). "Interestingly, very few CD3, CD4, CD8, CD204, FoxP3+ and mast cells were identified in the periodontitis lesions." (PMID 31923271, 2020). "The expression of Rorc in CD4+ T cells sorted from cervical lymph nodes was increased during periodontitis in wild-type mice, but not in Il6–/– mice." (PMID 29453398, 2018). "The periodontitis-induced bone loss and osteoclast number were significantly reduced, albeit to a lesser extent, when RANKL was deleted in T cells (Cd4-Cre) but not B cells (Mb1-Cre)." (PMID 29453398, 2018). "Among the CD4+ T-cell subsets, TH17 cells exclusively accumulated in the oral mucosa and draining lymph nodes during oral infection, consistent with high expression of TH17-related cytokines Il17a and Il6 in the oral mucosa of periodontitis-induced mice." (PMID 29453398, 2018). "Moreover, T cell-mediated adaptive immune responses are crucial in the development of periodontitis, and upon activation through the T cell receptor (TCR), naive CD4+ T cells can differentiate into Th1, Th17, and Treg cells and participate in different types of immune responses." (PMID 36923589, 2023). "However, this approach has not been evaluated in senescent CD4+ T lymphocytes in the context of diseases with inflammatory osteolysis, such as periodontitis." (PMID 35269683, 2022). "We found that the fraction of CD4+/CD8+ T cells in periodontitis tissue was significantly depressed, which might be one of the factors contributing to the suppression of the immune microenvironment in periodontitis tissues." (PMID 33841510, 2021). "Although these CD4+ T cell subclusters may perform distinct functions in the microenvironment of periodontal tissues, no statistical significance was detected during the periodontitis process." (PMID 35154475, 2022). "In a human study, the frequency of CD4 + and CD8 + T cells in PBMCs was not related to the periodontitis status." (PMID 39342169, 2024). "Infection duration, CD4 count and CD4/ CD8 ratio, as well as type of cART, were not significantly different between the severe periodontitis and moderate periodontitis groups." (PMID 36316604, 2023). "CD4+ T cells preferentially upregulated IL-17 and not IFN-γ in gingival tissue from periodontitis patients." (PMID 31416146, 2019). "The presence or absence of periodontitis was assessed and the peripheral blood (PB) concentrations of IL-6, immunosuppressive cytokines (VEGF, TGF-β1, and CCL22) and proportion of T regulatory cells (Treg, CD3 + CD4 + CD25 + Foxp3 +) were measured." (PMID 35804048, 2022).
lung adenocarcinoma (114 papers, 2011 to 2026). A carcinoma that arises from the lung and is characterized by the presence of malignant glandular epithelial cells. "Conversely, resting memory CD4+ T cells, linked to improved outcomes in lung adenocarcinoma, were also reduced." (PMID 40124684, 2025). "Further, CD44 activation of PD-L1 was shown to be associated with immune infiltration, as depletion of CD44 in lung adenocarcinoma cells was linked with B cell, CD4+ T cell, neutrophil and dendritic cell infiltration." (PMID 35269569, 2022). "In this study, our results showed low levels of B cells, CD4+ T cells, macrophages, neutrophils, and dendritic cells were associated with poor prognosis of lung adenocarcinoma patients, while high ALDOA expression was correlated with poor prognosis in lung adenocarcinoma patients." (PMID 34925439, 2021). "Using spatial proteomics of lung adenocarcinoma and adjacent tissue, we found that CD4+ AICL+ and CD8+ KLRF1+ T cells are enriched and spatially interacting in non-tumor regions, whereas both populations are reduced within tumor tissue." (PMID 41851343, 2026). "TLR7 expression in lung adenocarcinomas correlates with immune infiltration levels, including B cells, CD4+ T cells, CD8+ T cells, dendritic cells, and macrophages." (PMID 39857735, 2025). "Previous research has shown high expression of the Sdcbp gene in lung adenocarcinoma and squamous cell carcinoma significantly correlated with elevated markers for CD4+ T cells, CD8+ T cells, and macrophages." (PMID 41614830, 2025). "Knockdown of HIF-1α blocked hypoxia-induced recruitment of CD4+CD25+ Treg cells in lung adenocarcinoma cell lines." (PMID 39232704, 2024). "This study aimed to investigate TAGAP’s expression and its potential impact on CD4+ T cell function and prognosis in lung adenocarcinoma (LUAD)." (PMID 37744350, 2023). "The level of infiltrating resting CD4 memory T cells was favorably correlated with HS6ST2 expression in lung adenocarcinoma, pancreatic adenocarcinoma, and thyroid carcinoma but inversely correlated with HS6ST2 expression in sarcoma." (PMID 37932473, 2023). "An immunosuppressive microenvironment enriched with regulatory CD4+ T lymphocytes (Tregs) facilitates the progression of lung adenocarcinoma (LUAD)." (PMID 37532692, 2023). "The results demonstrated that overexpression of TAGAP significantly enhanced the cytotoxicity of CD4+ T cells against lung adenocarcinoma cells compared to the control group, with the highest cytotoxicity observed at the T:E ratio of 1:5." (PMID 37744350, 2023). "The expression of immune cells was involved in the infiltration of CD4+ T cells, macrophages, and dendritic cells in lung adenocarcinoma (LUAD)." (PMID 36688087, 2023). "CCNB2 and AURKB were negatively correlated with B cells, macrophages, myeloid dendritic cells and CD4+T-cell infiltration in lung adenocarcinoma." (PMID 36909154, 2023). "The Kaplan–Meier plotter revealed an association between high levels of J chain mRNA and good prognosis in lung adenocarcinoma patients that correlated with increased B and CD4 T cells and reduced Tregs and M2 macrophages." (PMID 36361537, 2022). "Above all, we believe IL7R inhibits the progression of lung adenocarcinoma by modulating the infiltration levels of B cells, DC cells, and CD4 + T cells, thus affecting the survival of patients." (PMID 35264973, 2022). "One study using a mouse model of lung adenocarcinoma demonstrated that the LNME skews tumour antigen-specific CD4+ differentiation into regulatory T cells, thus promoting tumour immune escape." (PMID 34439160, 2021). "Meanwhile, the activation of resting memory CD4+ T cells has been reported to contribute to the progression and development of lung adenocarcinoma." (PMID 34512623, 2021). "In this study, we demonstrated a prognostic role for tumor infiltrating CD4+ LAIR2+ Treg cells in lung adenocarcinoma." (PMID 35008369, 2021).
lung adenocarcinoma (continued). "The association of Treg depletion with increased CD4+ and CD8+ T cell infiltration and TLS formation in carcinogen-induced tumors and lung adenocarcinoma models also demonstrates cross-talk between Tregs and TLS." (PMID 33763071, 2021). "The data from this study collectively indicated that miR-195 is able to act as an inhibitor of lung adenocarcinoma by enhancing CD4+ T cell activity via the CCDC88C/Wnt signalling pathway." (PMID 34680611, 2021). "We also confirmed that ALDOA gene expression was inversely correlated with infiltrating levels of B cells, CD8+ T cells, CD4+ T cells, and macrophages in lung adenocarcinoma." (PMID 34925439, 2021). "In the present study, we reported that ALDOA copy number alterations were correlated with immune infiltration levels of B cells, CD8+ T cells, and CD4+ T cells in lung adenocarcinoma by TIMER." (PMID 34925439, 2021). "One such study identified that miR-195 is potentially involved in inhibiting lung adenocarcinoma progression by enhancing CD4+ T cell activation." (PMID 34680611, 2021). "Further analysis identified that CD4+ T cells were the subset of lymphocytes involved in infiltration of lung adenocarcinoma through activation of miR-195-targeted genes." (PMID 34680611, 2021). "We further analyzed the association between various forms of CD44 copy number and immune cells B cell, CD8+ T cell, CD4+ T cell, macrophage, neutrophil and dendritic cell infiltration in lung adenocarcinoma." (PMID 33372595, 2020). "FGL2 was positively correlated with the infiltration of immune cells, including dendritic cells, CD8+ T cells, macrophages, B cells, and CD4+ T cells, in lung adenocarcinoma." (PMID 32206449, 2020). "FGL2 was positively correlated with the infiltration of immune cells, including CD8+ T cells, CD4+ T cells, macrophages, B cells and dendritic cells, in lung adenocarcinoma." (PMID 32206449, 2020). "To test the ability of the G-baToN system to capture cancer cell-T cell interactions in vivo, we established lung tumors from a sGFP-expressing lung adenocarcinoma cell line prior to intravenous transplantation of αGFP-expressing CD4 T cells." (PMID 33025906, 2020). "To this end, we quantified CD4 T cells reactive to lung adenocarcinoma antigens using IFN‐γ‐activated autologous monocyte‐derived DCs as antigen presenting cells, as described." (PMID 31273938, 2019). "mRNA expression corresponding to Notch1 was significantly elevated in peripheral CD4+ T cells purified from lung adenocarcinoma patients in comparison with those from NCs (approximately five-fold induction, P<0.0001)." (PMID 30473538, 2018). "In the present study, we found that Notch1 mRNA, but not Notch2 mRNA, was elevated in both peripheral and lung-resident CD4+ T cells in lung adenocarcinoma patients." (PMID 30473538, 2018). "Here we show, using a genetically engineered lung adenocarcinoma mouse model, that naive tumor-specific CD4+ T cells are activated and proliferate in the tumor-draining lymph node (TdLN) but do not differentiate into effectors or accumulate in tumors." (PMID 29844317, 2018). "In this work, we use an improved lentivirus (LV) based genetically engineered lung adenocarcinoma model to characterize the fate of naive CD4+ T cells following the recognition of a tumor-specific cytoplasmic Ag." (PMID 29844317, 2018). "EMT was associated with exclusion of immune cells critical in the immune response to cancer, with significantly lower infiltration of CD4 T-cells in lung adenocarcinoma and CD4/CD8 T-cells in squamous cell carcinoma." (PMID 29440769, 2018). "In conclusion, elevated Notch1 induced higher IL-22 secretion by CD4+ T cells in lung adenocarcinoma patients, and Notch-AhR-IL-22 axis took part in the pathogenesis of lung adenocarcinoma." (PMID 30473538, 2018).